RIPK1 (receptor interacting serine/threonine kinase 1)
Diseases named in the same sentence as RIPK1 in open-access papers (continued):
Sharing a sentence is not in itself a finding about the gene and the disease.
colitis (continued). "Mice with intestinal-epithelial cell (IEC)-specific ablation of NEMO (NEMOIEC-KO) spontaneously develop severe colitis, which is caused by TNF-induced RIPK1 kinase-dependent death of IECs15,47." (PMID 32269263, 2020). "As a result, RIPK1 kinase inhibitors have been advanced into the human clinical trial for the treatment of colitis, amyotrophic lateral sclerosis, and Alzheimer’s diseases." (PMID 29703889, 2018). "Although one study had reported that necrostatin-1, a RIPK1 kinase inhibitor, reduces intestinal inflammation, studies on the protective effect of necroptosis inhibitors against colitis are few." (PMID 29156831, 2017). "A previous case study reported the use of anakinra (3 mg/kg) in a patient with RIPK1-deficiency and refractory colitis but the response was not documented." (PMID 39762600, 2025). "Also, presented with VEO-IBD, the deficiency of the receptor-interacting protein kinase 1 (RIPK1) gene inhibits NLRP3 inflammasome activation upon lipopolysaccharide stimulation, participating in human colitis." (PMID 41149694, 2025). "Tumor necrosis factor signaling through the RIPK1 pathway regulates colitis, and therefore, the inhibition of RIPK1 may be a potential beneficial goal for ulcerative colitis (UC) treatment." (PMID 39770124, 2024). "They presented with colitis and recurrent infections, also some of them had polyarthritis, aphthous ulcers, and perianal disease that comparable to our patient, because of the critical role of RIPK1 in controlling human immune and intestinal homeostasis." (PMID 38676845, 2024). "Many studies have reported that RIPK1 inhibitors present an opportunity to treat a range of human degenerative and inflammatory diseases, including colitis, dermatitis, traumatic brain injury, stroke, lysosomal storage diseases, amyotrophic lateral sclerosis (ALS), and multiple sclerosis (MS)." (PMID 36050939, 2022). "The results showed that RI-962 reduced the levels of pRIPK1, pRIPK3, and pMLKL proteins in the colon during DSS challenge, but did not impact the expression of RIPK1, RIPK3, and MLKL proteins, suggesting that RI-962 suppressed the RIPK1 signaling in the mouse model of DSS-induced colitis." (PMID 36371441, 2022). "We examined whether apoptosis and/or necroptosis was involved in the protective effect of DC-specific deletion of RIPK1 on DSS-induced colitis." (PMID 34462571, 2022). "Indeed, pharmacological inhibition of RIPK1 kinase activity has been shown to be effective in the murine CD4+CD45RBHI T-cell transfer model of colitis and provided dose-dependent protection from inflammatory cell death in NemoVillin.cre/+ mice." (PMID 33924766, 2021). "For example, loss of IKK complex component NEMO in IECs (Villin cre) results in spontaneous colitis mediated by TNFR1 signalling and RIPK1 kinase-dependent cell death, while IKKβ protects against colitis induced by Clostridium difficile or dextran sodium sulphate (DSS)." (PMID 33924766, 2021). "Interestingly, blocking RIPK1 by Nec-1s in vivo and in vitro dramatically alleviates colitis and cell death, which share the same phenotype with ABIN1 overexpression; hence, ABIN1 activation may be considered a therapeutic strategy for UC." (PMID 39118979, 2024). "It is worth noting that whether necroptosis or the kinase activity of RIPK1 is necessary for DSS-induced colitis is still debatable, so we speculate that PPP6C might play a more complex role in regulating tissue injury and inflammation beyond its ability to promote necroptosis." (PMID 35842423, 2022). "Blocking RIPK1 by Nec-1s in vivo (DSS-induced colitis in mice) and in vitro (TNF-α induced inflammation in the IEC cell line) dramatically alleviated the colitis and cell death which shares the same phenotype with ABIN1 overexpression." (PMID 36034412, 2022).
colitis (continued). "These authors suggested a therapeutic potential for receptor-interacting serine/threonine-protein kinase 1 (RIPK1) inhibition in IBD patients, after demonstrating that RIPK1 prevented epithelial cell death and colitis development in NEMOIEC−KO mice." (PMID 36012618, 2022). "The colitis in mice with conditional IEC knockout of NEMO, FADD, CASP8, and RIPK1 mice is largely reversed by TNF or TNFR1 deletion." (PMID 35077396, 2022). "Nec-1, a RIPK1 inhibitor, suppresses DSS-induced colitis, but it is also an inhibitor of indoleamine 2,3-dioxygenase, which contributes to development of colitis." (PMID 31019191, 2019). "Taken together, we discover HtrA2 as a positive regulator of necroptosis and colitis by degrading RIPK1 and our results suggest UCF-101 as a potential candidate for anti-colitis therapy in the future." (PMID 31019191, 2019). "Our results support that IPA, a bacterial metabolite, may block the epithelial necroptosis by inhibiting the RIPK1/RIPK3/MLKL pathway, which may give a rational explanation for the lower concentration of its in both colonic tissue and serum of colitis." (PMID 40745657, 2025). "We found that ABIN1, RIPK1, RIPK3, and MLKL were upregulated in UC samples and DSS-induced colitis." (PMID 36034412, 2022). "We found that ABIN1, RIPK1, RIPK3, and MLKL were upregulated in UC sample and DSS-induced colitis." (PMID 36034412, 2022). "Nonetheless, CD11c;Ripk1fl/fl littermates were significantly more resistant to DSS-induced colitis than Ripk1fl/fl mice, indicating that expression of kinase inactive RIPK1 in non-DC cell types did not contribute to the resistance to DSS." (PMID 34462571, 2022). "Loss of upstream TAK1 in IECs triggers TNFR1-dependent (presumably RIPK1-dependent) apoptosis and intestinal inflammation, although colitis and ileitis ultimately develop in the absence of TNFR1." (PMID 33924766, 2021). "Indeed, CRIF1 overexpression reduced the numbers of cells expressing TNF-α, TNFR1, RIPK1, RIPK3, and phosphorylated MLKL in our experimental mice, suggesting that CRIF1 overexpression can downregulate intestinal inflammatory cell death in colitis." (PMID 40821844, 2025). "In our GEO data analysis of UC patients, “Pyroptosis”, “Regulated necrosis”, and “Apoptosis” were positively correlated with UC patients, which supports our result showing increased expression of RIPK1 and RIPK3, but not ALOX12 and GPX4, in the acute colitis model." (PMID 38491049, 2024).
amyotrophic lateral sclerosis (36 papers, 2018 to 2025). Amyotrophic lateral sclerosis (ALS) is a neurodegenerative disease characterized by progressive muscular paralysis reflecting degeneration of motor neurons in the primary motor cortex, corticospinal tracts, brainstem and spinal cord. "RIPK1 has been implicated in the pathophysiology of a number of degenerative illnesses, such as amyotrophic lateral sclerosis, as well as neurodegenerative and inflammatory diseases." (PMID 37643315, 2023). "The activation of RIPK1 has also been implicated in mediating inflammatory responses in neurodegenerative diseases such as amyotrophic lateral sclerosis (ALS), multiple sclerosis (MS) and Alzheimer’s disease." (PMID 36969188, 2023). "Ripk1/Ripk3 associated with marked neuroinflammation in animal models of diseases such as multiple sclerosis, amyotrophic lateral sclerosis and Alzheimer’s disease and their inhibition improved the disease phenotype." (PMID 34172992, 2021). "Interestingly, an aging-associated reduction of TAK1 expression was shown to cooperate with other genetic risk factors to promote the RIPK1-dependent onset of neuroinflammation and the development of amyotrophic lateral sclerosis (ALS) in humans." (PMID 31850239, 2019). "Several chronic neurodegenerative diseases, such as amyotrophic lateral sclerosis (ALS), Alzheimer’s disease (AD), and Parkinson’s disease (PD), are also linked to increased activation of RIPK1." (PMID 39062098, 2024). "More recently, optineurin, mutations of which are associated with amyotrophic lateral sclerosis (ALS), was shown to trigger degradation of RIPK1 and its loss lead to axonal degeneration." (PMID 31131275, 2019). "It directly binds to and regulates the function of caspase-8, of proteasome-mediated RIPK1 stability in amyotrophic lateral sclerosis, as well as vesicle trafficking and autophagy, and therefore represents a promising regulator of vesicular ADAM15." (PMID 41340056, 2025). "Previous studies showed that an age-dependent reduction in TAK1 expression is associated with neurodegenerative diseases, such as frontotemporal dementia/amyotrophic lateral sclerosis, and inhibition of RIPK1 was found to alleviate disease-like symptoms." (PMID 37329446, 2023). "The RIPK1 increase has been observed in the microglia of AD, amyotrophic lateral sclerosis (ALS), and multiple sclerosis (MS) mouse models, and the RIPK1 inhibitor necrostatin-1 (Nec-1) treatment reduced proinflammatory cytokine expression." (PMID 36766759, 2023). "Selective inhibitor of RIPK1 such as necrostain-1 has been applied in stroke, traumatic spinal cord injury, and amyotrophic lateral sclerosis and reveals protection in CNS diseases." (PMID 33390995, 2020). "Another RIPK1 inhibitor DNL747 is currently in clinical development for the treatment of neurodegenerative diseases including Amyotrophic lateral sclerosis (NCT03757351) and Alzheimer’s disease (NCT03757325)." (PMID 31766571, 2019). "In CNS, both RIPK1 and RIPK3 are implicated in playing a role in neurological diseases such as multiple sclerosis, amyotrophic lateral sclerosis (ALS), AD, and PD by promoting neuroinflammation, cytokine production by microglia, and astrocyte and neuronal cell death." (PMID 39057755, 2024). "TNF-upregulation related necroptosis mediated by RIPK1 promotes further cell death and neuroinflammation in the pathogenesis of several neurodegenerative diseases including multiple sclerosis, amyotrophic lateral sclerosis (ALS), Parkinson disease and Alzheimer disease." (PMID 37996860, 2023). "Receptor-interacting protein kinase (RIPK1) mediates necroptotic cell death, induces ischaemic organ injury, and plays a role in chronic neurodegenerative conditions, such as multiple sclerosis, amyotrophic lateral sclerosis and Alzheimer’s disease." (PMID 37329446, 2023).
amyotrophic lateral sclerosis (continued). "Denali Therapeutics began a phase Ia clinical trial for SAR443060 (DNL747), a small-molecule, selective, orally bioavailable, central nervous system (CNS)-penetrant, reversible RIPK1 inhibitor, phase Ib/IIa trials in amyotrophic lateral sclerosis (ALS) and Alzheimer’s disease (AD) followed." (PMID 38129399, 2023). "Similarly, inhibition of necroptosis using Nec-1s, an allosteric inhibitor of RIPK1, has been shown to reduce neuroinflammation in Alzheimer’s disease, Parkinson’s disease, multiple sclerosis, and amyotrophic lateral sclerosis." (PMID 34515928, 2021). "The activation of RIPK1 kinase activity is involved in mediating pathological cell death and inflammation in a wide arrange of major human diseases from peripheral rheumatoid arthritis and Crohn’s disease to neurodegenerative disorders such as amyotrophic lateral sclerosis and Alzheimer’s disease." (PMID 36969188, 2023). "For example, hyperactivation of RIPK1 in Tbk1/Tak1 double heterozygous mice leads to comorbidity of amyotrophic lateral sclerosis (ALS) and frontotemporal dementia (FTD), which is attenuated by one allele of kinase-dead RIPK140." (PMID 34862394, 2021). "Inhibition of RIPK1 can effectively ameliorate the pathologies and promote remyelination in various neurodegenerative diseases including MS and amyotrophic lateral sclerosis (ALS) mainly mediated by protecting oligodendrocytes from necroptosis." (PMID 35365618, 2022). "Notably, increased RIPK1 kinase activity has been observed in animal models of AD, amyotrophic lateral sclerosis (ALS), and multiple sclerosis (MS), as well as in human patient samples, implying a potential contribution of this protein to the pathogenesis of these neurodegenerative disorders." (PMID 37396657, 2023). "Necroptosis is a form of regulated necrotic cell death, in which RIPK1/RIPK3 kinases mediate activation of the MLKL kinase, and is emerging as a relevant pathway of cell death in other neurodegenerative conditions, such as amyotrophic lateral sclerosis." (PMID 30989755, 2019). "TAK1 is an endogenous inhibitor of RIPK1, and an age-dependent reduction in TAK1 expression might be a key factor that contributes to neurodegenerative disease models, such as frontotemporal dementia and amyotrophic lateral sclerosis." (PMID 37329446, 2023). "Currently, several RIPK1 inhibitors, GSK′2982772, DNL747, and DNL758, are in phase 1 or 2 clinical trials targeting inflammatory diseases such as psoriasis, ulcerative colitis, severe rheumatoid arthritis, Alzheimer’s disease, amyotrophic lateral sclerosis, and COVID-1995,96." (PMID 34075202, 2021). "Hallmarks of necroptosis including the phosphorylation of RIPK1 and elevated levels of insoluble RIPK1, RIPK3 and MLKL are found in post-mortem human pathological samples such as patients with amyotrophic lateral sclerosis (ALS) and Alzheimer’s disease (AD)." (PMID 34689152, 2021).
psoriasis (35 papers, 2018 to 2025). An autoimmune condition characterized by red, well-delineated plaques with silvery scales that are usually on the extensor surfaces and scalp. "TNFR1 signalling via RIPK1 has been long recognised for its role in driving pathogenic pro-inflammatory cytokine and chemokine production in common diseases, such as Rheumatoid arthritis (RA), psoriasis, ankylosing spondylitis, and inflammatory bowel disease (IBD)." (PMID 33924766, 2021). "T cell activation, cytokine production, and inflammation can contribute to abnormal immune responses in psoriasis – all of which can be regulated by RIPK1 scaffolding function and kinase activity." (PMID 41019071, 2025). "In isolated psoriasis neutrophils, RIPK1 and caspase-8 mRNA were downregulated while RIPK3 and MLKL mRNA were elevated, suggesting enhanced RIPK3/ZBP1-mediated necroptosis." (PMID 41019071, 2025). "As such, diving deeper into how RIPK1 modulates the progression of psoriasis is of paramount importance." (PMID 40007541, 2025). "RIPK1 dysregulation contributes to psoriasis pathogenesis, but the therapeutic impact remains under investigation." (PMID 41019071, 2025). "Low levels of RIPK1 protein expression can be detected in monocytes and neutrophils from peripheral blood of psoriasis patients." (PMID 41019071, 2025). "This allows us to unequivocally identify RIPK1 as a therapeutic target in the treatment of inflammatory disorders, including psoriasis." (PMID 40494888, 2025). "A recent study has demonstrated necroptosis’s crucial role in psoriasis pathogenesis, evidenced by the significant upregulation of RIPK1 and MLKL throughout all epidermal layers in human psoriatic lesions." (PMID 40332377, 2025). "Psoriasis, a chronic skin condition, has drawn attention in the clinical realm, especially with RIPK1 inhibitors being tested in clinical trials as potential therapeutic agents." (PMID 40007541, 2025). "In a phase 2 multicenter randomized placebo-controlled study for psoriasis patients, treatment with a RIPK1 inhibitor improved the severity of plaque lesions compared with placebo without any severe drug-related adverse effects." (PMID 35013338, 2022). "In psoriasis, S. aureus infection can also be mediated by the RIPK1/RIPK3/MLKL-mediated necrotizing apoptosis of keratinocytes, and RIPK1 mediates keratinocyte death via TNF." (PMID 35878202, 2022). "The first human clinical trials of RIPK1-targetted small molecule compounds were conducted in cohorts of rheumatoid arthritis, ulcerative colitis and psoriasis patients." (PMID 34071602, 2021). "Oral RIPK1 inhibitor has been reported to be useful in inflammatory diseases, including psoriasis, inflammatory bowel disease, and rheumatoid arthritis." (PMID 33329521, 2020). "Recently, GSK developed a type II/III RIPK1 inhibitor (GSK2982772) that is currently in clinical trial phase IIa for the treatment of psoriasis, rheumatoid arthritis and ulcerative colitis." (PMID 29434255, 2018). "Therefore, RIPK1 is involved in autoimmune diseases, such as rheumatoid arthritis, psoriasis, and inflammatory bowel disease." (PMID 40004031, 2025). "Necroptosis, a form of regulated necrosis mediated by receptor-interacting protein kinase 1 (RIPK1), RIPK3, and mixed-lineage kinase domain-like pseudokinase (MLKL), plays a central role in the inflammatory cascade of psoriasis and is also implicated in other inflammatory diseases." (PMID 40906403, 2025). "In addition, the RIPK1 inhibitor GSK2982772 (compound 5) has the potential to become an effective treatment for psoriasis, rheumatoid arthritis, and ulcerative colitis." (PMID 40305291, 2025). "Currently ongoing clinical trials will teach us whether RIPK1 inhibitors can be used in skin inflammatory diseases such as psoriasis." (PMID 37688617, 2023).